RALGAPB (Ral GTPase activating protein non-catalytic subunit beta)
Description:
Non-catalytic subunit of the heterodimeric RalGAP1 and RalGAP2 complexes which act as GTPase activators for the Ras-like small GTPases RALA and RALB.
Synonyms: KIAA1219; DKFZp781M2411; RalGAPbeta
Tractability: PROTAC: ubiquitination databases record sites on it; its protein half-life has been measured.
Gene: Protein-coding gene on chromosome 20 (38,472,816 to 38,578,859, forward strand). Ensembl gene ENSG00000170471.
Subcellular location (Human Protein Atlas): Nuclear speckles
Pathways (Reactome):
Vesicle-mediated transport: Translocation of SLC2A4 (GLUT4) to the plasma membrane
Gene Ontology:
Molecular function: protein binding; protein heterodimerization activity; GTPase activator activity
Biological process: activation of GTPase activity; Ral protein signal transduction; regulation of small GTPase mediated signal transduction
Genetic constraint (gnomAD): Loss-of-function variants: 20 observed, 144.14 expected, observed/expected ratio (o/e) 0.14, 90% interval 0.097 to 0.2. The upper end of that interval is the gene's LOEUF score, 0.2, which puts it in group 1 of 6, group 1 being the genes least tolerant of losing a copy. Missense variants: 1,271 observed, 1,765.5 expected, observed/expected ratio (o/e) 0.72, 90% interval 0.69 to 0.75. Synonymous variants: 590 observed, 617.69 expected, observed/expected ratio (o/e) 0.96, 90% interval 0.89 to 1.02.
Homologues: Orthologues: chimpanzee RALGAPB (99% identical), macaque RALGAPB (99% identical), dog RALGAPB (98% identical), rabbit RALGAPB (98% identical), pig RALGAPB (98% identical), rat Ralgapb (98% identical), mouse Ralgapb (97% identical), guinea pig RALGAPB (97% identical), tropical clawed frog ralgapb (84% identical), zebrafish ralgapb (78% identical), Drosophila melanogaster CG34408 (43% identical), Caenorhabditis elegans hgap-2 (26% identical).
Diseases named in the same sentence as RALGAPB in open-access papers:
RALGAPB is named in the same sentence as 11 diseases in open-access papers, as found by Europe PMC text mining. Sharing a sentence is not in itself a finding about the gene and the disease. The quoted sentences say what the papers report.
breast carcinoma (2 papers, 2018 to 2022). "Applying Kaplan–Meier analyses, we found that up expression of RALGAPB was related to the poor OS in patients with Lum A breast cancer (p = 0.042)." (PMID 36412911, 2022). "We performed Kaplan–Meier and Cox proportional hazards regression analyses to verify if the signatures of NORAD and RALGAPB could predict the overall survival (OS) in breast cancer patients." (PMID 36412911, 2022).
Macrocephaly (2 papers, 2018 to 2022). Occipitofrontal (head) circumference greater than 97th centile compared to appropriate, age matched, sex-matched normal standards. "We identified a potential novel risk gene (ZNF292), one novel gene with recurrent LGD DNMs (RALGAPB), as well as genes associated with macrocephaly (GIGYF2 and WDFY3)." (PMID 30564305, 2018). "More studies are necessary to endorse RALGAPB as a possible candidate for macrocephaly." (PMID 36553552, 2022). "We retrieved from the DECIPHER database de novo <500 kb CNVs reported on patients with macrocephaly; in four cases, a candidate gene for macrocephaly could be pinpointed: a known microcephaly gene–TRAPPC9, and three genes based on their functional roles–RALGAPB, RBMS3, and ZDHHC14." (PMID 36553552, 2022).
acute pancreatitis (1 paper, 2025). An acute inflammatory process that leads to necrosis of the pancreatic parenchyma. "We next asked how RalGAPβ deficiency would affect outcome in case of an episode of acute pancreatitis." (PMID 40490362, 2025). "In agreement, RalGAPβ-deficient mice develop persistent ADM and inflammation upon a single episode of mild acute pancreatitis." (PMID 40490362, 2025).
oral squamous cell carcinoma (1 paper, 2022). "A study in oral squamous cell carcinoma showed that RALGAPB silencing increased the level of RalA activation, promoting HSC-2 cell migration and invasion in vitro, a profile characteristic of metastatic cells." (PMID 36412911, 2022).
pancreatic cancer (1 paper, 2025). "In addition, knockout of RalGAPβ in pancreatic tumor cell lines has been shown to promote migration, invasion, and metastasis in tissue culture and xenograft models." (PMID 40490362, 2025).
pancreatitis (1 paper, 2025). Inflammation of the pancreas. "We now demonstrate that RalGAPβ deficiency in the pancreas results in pancreatitis and neoplasia." (PMID 40490362, 2025). "As a result, reduction of RalGAPβ expression alone is sufficient to induce pancreatitis and neoplasia, demonstrating the importance of this understudied Ras effector pathway in pancreatic pathology." (PMID 40490362, 2025). "The ADM score was slightly but not significantly higher in RGβKO mice in comparison with control littermates upon pancreatitis induction, suggesting that RalGAPβ deficiency does not render the pancreas more susceptible to injury." (PMID 40490362, 2025).
tumor (5 papers, 2018 to 2025). "Here, we show that pancreatic RalGAPβ deficiency alone is sufficient to induce inflammation and neoplasia in vivo." (PMID 40490362, 2025). "In agreement, RalGAPβ loss dramatically accelerates tumor development when combined with mutant KRasG12D expression." (PMID 40490362, 2025). "In combination with an oncogenic KRASG12D mutation, RalGAPβ deficiency leads to a dramatic shortening of tumor latency and median survival." (PMID 40490362, 2025). "Having identified that RalGAPβ deficiency has additional cellular effects in comparison with κB-Ras loss, we wanted to understand how this would affect tumor development triggered by KRas mutation." (PMID 40490362, 2025). "Our current study addresses the in vivo effects of RalGAPβ loss in the pancreas in genetically modified mouse models, which allows us to study their impact on physiological functions, as well as tissue inflammation and (early) tumor development." (PMID 40490362, 2025). "When combined with oncogenic KRasG12D mutant expression, RalGAPβ deletion promoted tumor development, resulting in fully invasive PDAC at an age of 3 wk in all animals examined." (PMID 40490362, 2025). "To provide structural insights into the role of RalGAP complexes as tumor suppressors, we searched for missense mutations in the RALGAPA1, RALGAPA2, and RALGAPB genes in cancer patients." (PMID 40738882, 2025). "One of them carried a partial deletion of RALGAPB, a known tumor suppressor, which inhibits cell proliferation and tumor growth." (PMID 36553552, 2022). "Despite the limited specificity, the RALGAPB gene showed a high sensitivity to identify both Lum A and Basal-like subtypes compared to non-tumor samples, suggesting a modest potential as a biomarker." (PMID 36412911, 2022). "An analysis of pancreas development in RGβKO/R mice and/or deletion of RalGAPβ in the adult pancreas will be required to clearly delineate whether and how the phenotype we observed mechanistically relates to tumor formation in a fully formed pancreas." (PMID 40490362, 2025). "The signature of NORAD and RALGAPB in Lum A and Basal-like subtypes can predict a worse or better prognosis according to the survival of patients, and also has the potential to discriminate tumor and non-tumor groups." (PMID 36412911, 2022). "Knockout of RalGAPβ increases migration and invasion of PDAC (pancreatic ductal adenocarcinoma) cell lines as well as xenograft growth in vivo and accelerates local tumor growth and metastasis." (PMID 40738882, 2025).
infection (1 paper, 2021). The state of being infected such as from the introduction of a foreign agent such as serum, vaccine, antigenic substance or organism. "Identical effects on LC3 lipidation concurrent with a slight reduction in M2 expression levels were observed in infection of RalGAPβ−/− clone B8—which was generated using a different sgRNA to clone A4—or the RalGAPα1α2−/− cell line." (PMID 34706226, 2021). "RalGAPβ−/− cells clone A4 and WT cells were infected with IAV strain PR8 and LC3 lipidation at different time points post-infection (p.i.)analyzed by western blot." (PMID 34706226, 2021).
RALGAPB also shares sentences with these, for which no sentence is quoted: cancer (2 papers); lung carcinoma (1); microcephaly (1).